ABHD5 (abhydrolase domain containing 5, lysophosphatidic acid acyltransferase)
Description:
Coenzyme A-dependent lysophosphatidic acid acyltransferase that catalyzes the transfer of an acyl group on a lysophosphatidic acid. Functions preferentially with 1-oleoyl-lysophosphatidic acid followed by 1-palmitoyl-lysophosphatidic acid, 1-stearoyl-lysophosphatidic acid and 1-arachidonoyl-lysophosphatidic acid as lipid acceptor. Functions preferentially with arachidonoyl-CoA followed by oleoyl-CoA as acyl group donors (By similarity). Functions in phosphatidic acid biosynthesis. May regulate the cellular storage of triacylglycerol through activation of the phospholipase PNPLA2. Involved in keratinocyte differentiation. Regulates lipid droplet fusion (By similarity).
Synonyms: NCIE2; CGI-58; CGI58; IECN2
Tractability: Small molecule: a high-quality ligand is known. PROTAC: ubiquitination databases record sites on it; its protein half-life has been measured; a small molecule that binds it is known.
Gene: Protein-coding gene on chromosome 3 (43,690,108 to 43,734,371, forward strand). Ensembl gene ENSG00000011198.
Subcellular location: Cytoplasm; Lipid droplet; Cytoplasm, cytosol
Subcellular location (Human Protein Atlas): Cytosol; Vesicles; Nucleoplasm
Pathways (Reactome):
Metabolism: Triglyceride catabolism
Gene Ontology:
Molecular function: 1-acylglycerol-3-phosphate O-acyltransferase activity; lysophosphatidic acid acyltransferase activity; protein binding; triacylglycerol lipase activity; lipase activator activity
Biological process: phosphatidic acid biosynthetic process; positive regulation of triglyceride catabolic process; positive regulation of lipid catabolic process
Cellular component: cytoplasm; cytosol; lipid droplet
Genetic constraint (gnomAD): Loss-of-function variants: 29 observed, 42.89 expected, observed/expected ratio (o/e) 0.68, 90% interval 0.5 to 0.92. The upper end of that interval is the gene's LOEUF score, 0.92, which puts it in group 3 of 6, group 1 being the genes least tolerant of losing a copy. Missense variants: 393 observed, 433.4 expected, observed/expected ratio (o/e) 0.91, 90% interval 0.83 to 0.99. Synonymous variants: 166 observed, 153.48 expected, observed/expected ratio (o/e) 1.08, 90% interval 0.95 to 1.23.
Gene-disease validity (ClinGen):
ClinGen rates the evidence that ABHD5 causes each of these diseases.
Dorfman-Chanarin disease (autosomal recessive): Definitive.
Homologues: Orthologues: chimpanzee ABHD5 (99% identical), macaque ABHD5 (99% identical), dog ABHD5 (98% identical), rabbit ABHD5 (98% identical), mouse Abhd5 (95% identical), rat Abhd5 (95% identical), guinea pig ABHD5 (89% identical), pig ABHD5 (88% identical), tropical clawed frog abhd5 (74% identical), Drosophila melanogaster puml (48% identical), Caenorhabditis elegans C31H5.1 (13% identical), Caenorhabditis elegans F35H12.5 (12% identical), and 5 more. Paralogues in human: ABHD4 (54% identical), EPHX4 (20% identical), EPHX2 (20% identical), MEST (18% identical), EPHX3 (18% identical), ABHD6 (15% identical), ABHD8 (15% identical), ABHD11 (14% identical), ABHD14A (13% identical), BPHL (13% identical), SERHL2 (13% identical), ABHD14B (12% identical).
Diseases named in the same sentence as ABHD5 in open-access papers:
ABHD5 is named in the same sentence as 64 diseases in open-access papers, as found by Europe PMC text mining. Sharing a sentence is not in itself a finding about the gene and the disease. The quoted sentences say what the papers report.
Chanarin-Dorfman syndrome (43 papers, 2008 to 2026). "The Chanarin-Dorfman syndrome is an autosomal recessive inherited neutral lipid storage disease with ichthyosis (NLSDI) caused by mutations in ABHD5." (PMID 38835422, 2023). "In humans, variants in ABHD5 cause Chanarin-Dorfman syndrome, a neutral lipid storage disease with ichthyosis." (PMID 34791225, 2022). "Mutations in the ABHD5 gene cause Chanarin-Dorfman syndrome wherein the ability of ABHD5 to activate members of the PNPLA family is disrupted and results in disrupted lipid metabolism in numerous organs throughout the body." (PMID 35836935, 2022). "Chanarin–Dorfman syndrome (CDS) is a neutral lipid storage disease with ichthyosis caused by homozygous mutations in α/β hydrolase domain containing 5 (ABHD5) gene, also known as comparative gene identification-58 (CGI-58)." (PMID 36107452, 2022). "Loss-of-function mutations in the ABHD5 gene have been identified as an underlying cause of the Chanarin-Dorfman syndrome (CDS, OMIM:275630), a genetic subtype of neutral lipid storage disease (NLSD) with an estimated prevalence of less than 1:1,000,000." (PMID 36355098, 2022). "Loss of function mutations in ABHD5 result in Chanarin–Dorfman Syndrome (CDS), characterized by ectopic lipid accumulation in numerous cell types and severe ichthyosis." (PMID 35173175, 2022). "Here we report a case of Chanarin-Dorfman syndrome due to a de novo mutation in ABHD5 combined with uniparental isodisomy of maternal chromosome 3." (PMID 34440338, 2021). "We started by searching for mutations in ABHD5 (αβ-hydrolase domain-containing 5), the gene implicated in Chanarin–Dorfman syndrome (MIM 275630)." (PMID 35046931, 2021). "Here we report the first case of Chanarin-Dorfman syndrome due to a de novo ABHD5 mutation in the maternal germ cell, combined with a maternal uniparental isodisomy of chromosome 3." (PMID 34440338, 2021). "Specifically, ABHD5 mutations cause the Chanarin-Dorfman Syndrome, which is always associated with ichthyosis, a condition that is not observed with the ATGL mutations." (PMID 32542055, 2020). "In humans, mutations in the gene encoding ABHD5 are causally linked with Chanarin Dorfmann Syndrome, also designated as neutral lipid storage disease with ichthyosis (NLSD-I)." (PMID 32290093, 2020). "Chanarin-Dorfman syndrome (CDS) is a rare autosomal recessive metabolic disorder caused by mutations in gene encoding the domain-5 of α/β-hydrolase enzyme (ABHD5)." (PMID 29475365, 2018). "ABHD5 is the causative gene for the Chanarin-Dorfman syndrome (CDS), a neutral lipid storage disorder associated with ichtyosis." (PMID 27124600, 2016). "In humans, mutation of ABHD5 is associated with Chanarin-Dorfman syndrome, a rare disease characterized by neutral lipid storage (OMIM 275630)." (PMID 24652767, 2014). "Mutations in ABHD5 gene are associated with the onset of Chanarin-Dorfman syndrome (CDS), a rare autosomal recessive lipid storage disorder, characterized by non-bullous congenital ichthyosiform erythroderma (NCIE), hepatomegaly and liver steatosis." (PMID 24628803, 2014). "Mutations in the ABHD5 gene, encoding Abhydrolase Domain Containing 5, Lysophosphatidic Acid Acyltransferase, have been identified in patients with Chanarin–Dorfman Syndrome, a rare autosomal recessive disorder characterized by triglyceride accumulation in various tissues." (PMID 39769211, 2024). "Lastly, 3 variants, including the nonsense p.Glu295*, were found in ABHD5, associated with Chanarin–Dorfman syndrome (aka neutral lipid storage disease with ichthyosis); and 5 variants, including the known pathogenic p.Asp221Asn allele, in ALDH3A2, associated with Sjogren–Larsson syndrome." (PMID 38791074, 2024). "The detection of biallelic mutations in ABHD5 led to the diagnosis of Chanarin–Dorfman syndrome." (PMID 38540347, 2024).
Chanarin-Dorfman syndrome (continued). "The α/β-Hydrolase domain-containing protein 5 (ABHD5; also known as comparative gene identification-58, or CGI-58) is the causative gene of the Chanarin-Dorfman syndrome (CDS), a disorder mainly characterized by systemic triacylglycerol accumulation and a severe defect in skin barrier function." (PMID 36355098, 2022). "Mutations in ABHD5 disrupt lipolysis and are known to cause the Chanarin-Dorfman syndrome." (PMID 35836935, 2022). "Importantly, we structurally classified ABHD5 nsSNPs based on their geometric locations and characterized their functionally defective roles that are highly associated with human Chanarin-Dorfman Syndrome." (PMID 35173175, 2022). "The mutationof ABHD5 gene causes the human Chanarin-Dorfman Syndrome or NeutralLipid Storage Disease with Ichthyosis (NLSDI), which is a rare autosomalrecessive disorder characterized by the presence of intracellularaccumulation of triacylglycerol (TG) droplets in many tissues." (PMID 34213320, 2021). "A mutation of the ABHD5 gene could lead to a rare genetic disorder called Chanarin-Dorfman Syndrome because such patients accumulate excess triacylglycerol caused by a functional defect in ABHD5 in certain tissues and ichthyosis." (PMID 29794032, 2018). "Interestingly, mutations of ABHD5 associated with the Chanarin-Dorfman syndrome prevented the protein association with lipid droplets, abrogated its lipolytic activity but also its proviral function." (PMID 27124600, 2016). "Finally, ABHD5 is associated with the Chanarin-Dorfman syndrome, a rare human genetic lipid metabolism disorder." (PMID 27124600, 2016). "The enzymatic activity of PNPLA1 is enhanced by ABHD5, which may present triglycerides to PNPLA1 to facilitate substrate recognition, providing a mechanism whereby ABHD5 mutations cause Chanarin-Dorfman syndrome accompanied by ichthyosis with impaired ω-O-acylceramide formation." (PMID 33086624, 2020). "ABHD5-syndromic epidermal differentiation disorder (ABHD5-sEDD; also known as Chanarin-Dorfman syndrome) is a rare and severe autosomal recessive disorder that belongs to the group of Neutral Lipid Storage Diseases." (PMID 40818613, 2025). "As a rare metabolic disorder, Chanarin-Dorfman syndrome (CDS, OMIM: #275630) arises from defective lipid metabolism caused by mutations in gene encoding α/β-hydrolase domain-5 (ABHD5)." (PMID 29475365, 2018). "The genetic analysis of ABHD5 detected a novel deletion in the promoter region, confirming the diagnosis of Chanarin-Dorfman syndrome." (PMID 24628803, 2014). "Another member of this protein family, ABHD5, is thought to be responsible for a rare genetic disorder called Chanarin-Dorfman syndrome." (PMID 24795746, 2014). "Similarly, a genetic mutation in the ABHD5 gene, also known as CGI-58, reduces ABHD5 protein levels, leading to Chanarin-Dorfman syndrome and severe steatosis while preserving normal insulin sensitivity." (PMID 40507067, 2025). "Mutations in human CGI-58, also known as α/β hydrolase domain-containing 5 (Abhd5), lead to Chanarin-Dorfman syndrome (CDS), a rare autosomal recessive neutral lipid storage disease characterized by ichthyosis and the accumulation of TG-rich cytosolic LDs in all cell types." (PMID 40547297, 2025). "Defects in ABHD5 are known to cause Chanarin-Dorfman syndrome, a rare form of non-bullous congenital ichthyosiform erythroderma." (PMID 26398943, 2015). "This is reminiscent of the nuclear concentration of the Chanarin-Dorfman syndrome and engineered ABHD5 mutants that are incapable of binding the lipid droplets, and suggests that ABHD5 and ATGL might shuttle between nucleus and cytoplasm depending on their lipid droplet association." (PMID 32542055, 2020). "Collectively these results validate ABHD5 as novel HCV assembly co-factor and indicate that two variants of the protein involved in the Chanarin-Dorfman syndrome do not support HCV assembly." (PMID 27124600, 2016).
Chanarin-Dorfman syndrome (continued). "Chanarin-Dorfman syndrome (CDS), a rare genetic disorder marked by massive lipid droplet accumulation, offers compelling human evidence that α/β-hydrolase domain-containing protein 5 (ABHD5) plays a central role in lipid droplet mobilization through the ATGL axis." (PMID 41749838, 2026).
ichthyosis (35 papers, 2007 to 2025). Disorders of cornification that are characterized by visible scaling and/or hyperkeratosis of most or all of the skin. "The most defining clinical feature of ABHD5 deficiency, however, is the invariable onset of congenital ichthyosis, a severe skin disorder marked by dry, thickened skin with abnormal scaling, often involving the entire body surface." (PMID 40818613, 2025). "Given the importance of acylCers in maintaining skin barrier integrity, especially in the context of ichthyosis, we aimed to investigate how mutations in ABHD5 affect the protein's ability to stimulate PNPLA1." (PMID 40818613, 2025). "For example, it was shown that ABHD5 can also activate PNPLA1, and that mutations in PNPLA1 lead to LD accumulation and ichthyosis, similar to mutations in ABHD5." (PMID 40275410, 2025). "Here, we explore this critical gap in understanding epidermal lipid metabolism by examining frequent ABHD5 point mutants to decipher the molecular mechanism underlying ichthyosis pathogenesis in ABHD5-sEDD." (PMID 40818613, 2025). "Defects in the catabolism of TGs have been described in humans with ichthyosis-bearing mutations in the ABHD5/CGI-58 gene." (PMID 38727296, 2024). "Mutations in ABHD5 cause NLSDs with ichthyosis and additionally affect other organs, including liver, skeletal muscle, CNS and eyes." (PMID 33143278, 2020). "The reported data highlight the molecular mechanism via which ABHD5 mutations cause the onset of ichthyosis in NLSDI, since ὠ-O-acylceramide is an essential lipid for skin permeability barrier formation." (PMID 30795549, 2019). "ABHD5 mutations causing ichthyosis in humans are known to be associated with decreased levels of AcylCer." (PMID 30361410, 2018). "Mutations in the genes coding for patatin-like phospholipase domain-containing 1 (PNPLA1) and α/β-hydrolase domain-containing 5 (ABHD5), also known as comparative gene identification 58, are causative for ichthyosis, a severe skin barrier disorder." (PMID 30361410, 2018). "This strongly suggests an essential function of the C-terminal tail of ABHD5 and supports the hypothesis that the observed ABHD5:c.1006_1019del frameshift deletion is indeed causative for the ichthyosis in the investigated Golden Retrievers." (PMID 34791225, 2022). "Our data in dogs together with the knowledge on the effects of ABHD5 variants in humans strongly suggest ABHD5:c.1006_1019del as candidate causative genetic variant for a new canine form of ichthyosis, which we propose to designate as Golden Retriever ichthyosis type 2 (ICH2)." (PMID 34791225, 2022). "The ABHD5 gene encodes an acyltransferase related to lipid metabolism, and defects in this gene are related to Chanarin–Dorfman syndrome, a neutral lipid storage disease with ichthyosis." (PMID 36006348, 2022). "Mutations in ABHD5 may therefore specifically cause the ichthyosis by the reduced availability of these lipids." (PMID 33143278, 2020). "We recently found that AcylCer deficiencies occur in Dorfman–Chanarin syndrome (DCS), an autosomal recessive, neutral lipid storage disorder with ichthyosis, due to loss-of-function mutations in CGI-58 (α/β-hydrolase domain containing protein 5, ABHD5) in human skin." (PMID 23166695, 2012). "However, only mutations in the ABHD5 gene are linked to the pathogenesis of ichthyosis (NLSDI)." (PMID 36355098, 2022). "In this study, we identified a novel molecular mechanism driving the pathogenesis of ichthyosis in ABHD5-sEDD, shedding light on the complex interplay between epidermal lipid metabolism and skin barrier function." (PMID 40818613, 2025). "Our findings provide critical insights into the molecular basis of ichthyosis pathogenesis in ABHD5-sEDD." (PMID 40818613, 2025). "It was also noted that the coexistence of ichthyosis and Jordan’s anomaly was present in all DCS patients where the ABHD5 gene mutation was examined." (PMID 39457477, 2024).
ichthyosis (continued). "Neutral lipid storage disease with myopathy (NLSDM) and with ichthyosis (NLSDI) are rare autosomal recessive disorders caused by mutations in the PNPLA2 and in the ABHD5/CGI58 genes, respectively." (PMID 30795549, 2019). "Accordingly, mutations in the CGI58/ABHD5 gene, which encodes a putative triacylglycerol lipase, are responsible for the Chanarin-Dorman syndrome, a neutral-lipid storage disease with ichthyosis." (PMID 17562024, 2007). "Hence, a potential avenue to treat the ichthyosis from which the CDS patients suffer is topical gene therapy of ABHD5." (PMID 40275410, 2025). "In this syndrome, it was observed that regardless of the ABHD5 gene mutation, the presence of ichthyosis and lipid vacuoles (Jordan’s anomaly) in the cytoplasm of leukocytes, monocytes, and eosinophils provided differential diagnosis from other diseases." (PMID 39457477, 2024). "Most well documented forms of canine ichthyosis are non-epidermolytic, involving genetic variants in ABHD5 or PNPLA1 in golden retrievers, TGM1 in Jack Russell terriers, NIPAL4 in American bulldogs, and ASPRV1 in a German shepherd dog." (PMID 36251712, 2022). "Humans carrying mutant alleles of the lipolytic coactivator α/β-hydrolase domain-containing 5 (ABHD5), also designated as comparative gene identification 58, develop neutral lipid storage disease with ichthyosis [NLSDI; also referred to as Chanarin-Dorfman syndrome (OMIM: 275630)]." (PMID 30361410, 2018). "Conversely, alleles of ABHD5 carrying point mutations associated with ichthyosis in humans failed to accelerate PNPLA1-mediated AcylCer biosynthesis." (PMID 30361410, 2018). "Accordingly, humans carrying mutant alleles of ELOVL4, CYP4F22, or CERS3 develop a similar ichthyosis pathology as reported for ABHD5 and PNPLA1 deficiency due to the lack of ULC ω-hydroxy ceramides and AcylCer in the epidermis." (PMID 30361410, 2018). "The role of ABHD5 in epidermal lipid metabolism first became evident by the observation that individuals with ATGL deficiency, unlike those lacking functional ABHD5, do not exhibit ichthyosis, strongly suggesting that ABHD5 exerts an ATGL-independent function in the epidermis." (PMID 40818613, 2025). "Disease-associated amino acid substitutions in ABHD5 disrupt either its interaction with PNPLA1 or its localization to LDs, both of which ultimately impair PNPLA1 recruitment/localization and its enzymatic function, thereby leading to the pathogenesis of ichthyosis." (PMID 40818613, 2025). "While this finding established ABHD5 as a crucial regulator of lipolysis, it did not, however, explain the onset of ichthyosis in ABHD5-sEDD." (PMID 40818613, 2025). "Interestingly, these clinical features of ichthyosis or other skin abnormalities have not been reported in NLSDM patients or in ATGL-deficient mice, arguing for an ATGL-independent function of ABHD5 in skin physiology." (PMID 36355098, 2022).